HIF1A (hypoxia inducible factor 1 subunit alpha)
Diseases named in the same sentence as HIF1A in open-access papers (continued):
Sharing a sentence is not in itself a finding about the gene and the disease.
melanoma (continued). "First, STAT3 constitutive activity was shown to directly up-regulate Hif-1α transcription in melanoma cells, and to increase HIF-1α protein levels in several tumor cell types (e.g., breast, kidney, ovary, prostate, melanoma), correlating with EMT and invasion." (PMID 26106584, 2015). "Paradoxically, expression of MITF itself is reduced under hypoxic conditions in normal melanocytes and melanoma via direct binding of transcription repressor DEC1, which is activated by HIF1α." (PMID 24743024, 2014). "In the melanoma cell lines, ascorbate treatment at the individual IC50 concentrations decreased GLUT-1 expression (pro-survival HIF-1α downstream target)." (PMID 25202679, 2014). "MITF depletion in melanoma cells represses not only transcription of HIF1α but also that of vascular endothelial growth factor (VEGF), which is a target of HIF1α and has been demonstrated to be a major contributor to angiogenesis." (PMID 22046555, 2011). "Hypoxia can promote lymph node metastasis via up-regulation of PLAUR, and up-regulation of HIF1a, JUN and PLAUR in our invasive cell lines hints at possible activation of JUN/AP1 and HIF/ARNT pathways in melanoma." (PMID 20041153, 2009). "We also found that an mRNA splice variant, HIF-1α785, was expressed at higher levels than full length HIF-1α mRNA in the VGP and metastatic human melanoma cell lines." (PMID 19919690, 2009). "HIF-1α mRNA and protein was increased in RGP vs melanocytes, VGP vs RGP and MET vs VGP melanoma cell lines." (PMID 19919690, 2009). "In our studies a soluble formulation of 2ME2 effectively inhibited HIF-1α protein expression in vitro for three bone metastatic cell lines: MDA-MB-231 breast, PC-3 prostate and 1205Lu melanoma cells." (PMID 19727403, 2009). "Expression of selected hypoxia markers (HIF-1α, CAIX, TNF-α, Apaf-1) was significantly stronger in melanomas than in benign nevi, indicating possible roles in early melanoma development." (PMID 19061491, 2008). "Expression of selected hypoxia markers HIF-1α (p = 0.002), CAIX (p < 0.0001), TNF-α (p = 0.008) and Apaf-1 (p = 0.002) was significantly stronger in melanomas than in benign nevi." (PMID 19061491, 2008). "To further elucidate the connection between Hif1α and Hmox1, we subjected MLO-Y4 cells to Hif1α overexpression or an empty vector, followed by exposure to melanoma-derived CM or no treatment." (PMID 39814705, 2025). "In the hypoxic TME, hypoxia enhances IGF2BP1 expression levels by regulating the ability of hypoxia-inducible factor-1alpha (HIF-1α to bind to the IGF2BP1 promoter, subsequently increasing the proliferation and invasion potentials of melanoma cells, while decreasing their apoptotic rates." (PMID 40584294, 2025). "Vitamin C can reduce tumour growth, invasion and metastasis of melanoma in mice by inhibiting the hypoxia-inducible factor-1 alpha (HIF-1α) transcriptional activity, which might play a key role in melanoma carcinogenesis." (PMID 40776734, 2025). "The low levels of 5-hmC and the overexpression of HIF-1a in high-grade melanoma might suggest a correlation between TET enzymes and HIF-1a in the development of this malignancy." (PMID 40427015, 2025). "This suggests a potential clinical application for targeting HIF-1α in melanoma, regardless of the tumor’s hypoxic status." (PMID 40867277, 2025). "The epigenetic mechanism in the melanoma cells affecting PD-L1 expression resembles the previously observed mechanisms by which ARSB and chondroitin 4-sulfation affect galectin-3 and AP-1, as shown by transcriptional effects on HIF-1α, Wnt9a, and versican." (PMID 38892038, 2024). "Thus, HIF-1α can indirectly, via EMT induction, or directly via MITF/AXL expression, shift melanoma phenotypes towards immunosuppressive and metastatically-inclined states." (PMID 38426087, 2024). "However, this phenomenon was diminished by the activation of HIF-1α, demonstrating that TIPE promotes melanoma cell proliferation via dimeric PKM2-dependent HIF-1α activation." (PMID 39728923, 2024).
melanoma (continued). "In addition, silencing ET1 or using ETR inhibitors has been shown to lower HIF-1α and VEGF levels in endothelial cells and reduce angiogenesis in chondrosarcoma, ovarian cancer and melanoma cells." (PMID 38785410, 2024). "However, this phenomenon was diminished by activation of HIF-1α, demonstrating that TIPE promotes melanoma cells proliferation, glycolysis, and CSC properties via dimeric PKM2-dependent HIF-1α activation." (PMID 39728923, 2024). "Knockdown of LINC00518 or the addition of miR-33a-3p mimetics resulted in decreased levels of HIF-1α and LDHA proteins, while silencing HIF-1α in melanoma cells significantly reduced miR-33a-3p enrichment, indicating the presence of a negative feedback loop regulating tumor cell biological traits." (PMID 39108268, 2024). "In summary, our findings indicate that the TIPE/PKM2/HIF-1α signaling pathway plays a pivotal role in promoting CSC properties by facilitating the glycolysis, which would provide a promising therapeutic target for melanoma intervention." (PMID 39728923, 2024). "It was found that the inactivation of HIF1α and HIF2α selectively revokes metastasis without affecting the formation of primary melanoma, suggesting the prime role of HIF signaling in the development of metastatic tumors and shaping the metastatic niches." (PMID 38361941, 2024). "A noteworthy finding in melanoma is that LINC00518, by inhibiting miR-33a-3p expression and promoting its target gene hypoxia-inducible factor 1α (HIF-1α) expression, acts as an oncogene and directly regulates miR-33a-3p in a negative feedback loop, inducing radioresistance." (PMID 39108268, 2024). "Since HIF-1α pathway participates in metabolic reprogramming, especially aerobic glycolysis as well, we assumed that TIPE promotes melanoma progression might via the regulation of metabolic reprogramming." (PMID 39728923, 2024). "However, the identification of Hif-1α—overexpressed in BRAF-like tumours—as one of the orchestrators of metabolic processes in these tumours, likewise in melanoma, opens new intriguing therapeutic perspectives." (PMID 37198319, 2023). "LLLT increased the expression levels of HIF-1α and VEGF in B16F10 melanoma cells." (PMID 36836677, 2023). "Interestingly, in primary melanocytes and UACC62 melanoma cells, MITF expression has been shown to decrease under hypoxia in an HIF-1α-dependent manner." (PMID 36901857, 2023). "Moreover, the increase in HIF-1α induced by BRAF (V600E) mutation might significantly contribute to melanoma genesis in association with the PI3K/AKT/mTOR pathway, which is known to play a relevant role in early melanoma as well as resistance to BRAFi/MEKi therapy." (PMID 37895015, 2023). "Although not relevant in the D4M.3A melanoma cells used here, HIF-1α was shown to promote stem-like behavior and to be an inducer of the stem cell marker Nanog in B16 melanoma cells." (PMID 35406796, 2022). "In our study, both HIF-1a and HIF-2a correlated with low melanoma prognostic markers." (PMID 36294785, 2022). "Moreover, overexpression of SOX4 in melanoma leads to phosphorylation of AKT and activation of downstream HIF-1α and c-Myc to promote glycolysis in tumor cells." (PMID 36620597, 2022). "Similarly, it was found that LINC00518 promoted the migration, invasion, and metastasis of melanoma through the miR-204-5p/AP1S2 and miR-33a-3p/HIF-1α axes, which is consistent with our finding that LINC00518 serves as a risk factor for SKCM." (PMID 36371574, 2022). "In addition, luteolin impaired HIF-1α/VEGF and Notch1-VEGF signaling in melanoma and gastric cancer individually." (PMID 35784750, 2022).
melanoma (continued). "Furthermore, hypoxia and vascularization are mutually strengthening Numerous studies have shown that upregulation of HIF-1α/VEGF signaling pathway will promote tumor cell migration, invasion and melanoma angiogenesis." (PMID 36226170, 2022). "It was also demonstrated that HIF-1α is able to upregulate the expression of laminin-322, one of the main ECM elements secreted by keratinocytes, which was shown to promote adhesion and migration of melanoma cells." (PMID 33918883, 2021). "It was also demonstrated that lactate secreted into the melanoma microenvironment is taken up by endothelial cells via MCT1, where it induces HIF-1α, and thus leads to the upregulation of growth factors associated with angiogenesis including VEGFR2 and bFGF (basic fibroblast growth factor)." (PMID 33918883, 2021). "Lastly, IL-1β can upregulate HIF1α, known to inhibit MITF and increase melanoma invasiveness." (PMID 34604096, 2021). "Together, these results suggest that the reduction of intratumor production of HIF-1α and of pAP-1 c-Jun by combined liposomal therapy with LCL-SIM + LCL-DOX significantly weakened the invasive and metastatic ability of B16.F10 melanoma cells, via strong inhibition of MMPs activity." (PMID 34764332, 2021). "A study using a mouse model of melanoma found that inactivation of HIF-1α or HIF-2α had no change in tumorigenesis but significantly reduced metastasis, suggesting a specific function of HIF in metastasis." (PMID 33808542, 2021). "Cell viability test by the Tryptan Blue experiment exhibited inhibition of cell proliferation for melanoma A375 cells after HIF-1α and miR-210 gene silencing but not for siR neg cont melanoma cells in normoxia nor hypoxia." (PMID 33990669, 2021). "Although expression of HIF1α and bFGF was significantly higher in the melanoma compartment compared to other melanoma compartments, no such significant differences were seen with VEGF expression." (PMID 33552976, 2020). "As the PDPK1-AKT pathway, in addition to activating the transcription of HIF-1α, also promotes cell surface expression of GLUT1, inhibition of AKT phosphorylation by ACF might have a major impact on glucose metabolism in melanoma cells." (PMID 33396270, 2020). "By downregulating the activity of the HIF-1α/VEGF signaling pathway, Huaier may have an effect on angiogenesis of melanoma." (PMID 32596377, 2020). "This HIF-1α-dependent Cx43 expression in cardiac cells supports our previous evidence showing that HIF-1α binds GJA1 promoter, inducing Cx43 expression in hypoxic melanoma cells." (PMID 33066331, 2020). "Therefore, by inhibiting HIF-1α, ACF suppresses the Warburg effect and impedes the adaptation of melanoma cells to oxidative stress." (PMID 33396270, 2020). "Interestingly, by inhibiting the HIF-1α/PDK1 axis, ACF modulates the metabolism of glucose in melanoma cells." (PMID 33396270, 2020). "Moreover, we showed that the binding of Ku80 at the PDK-1 promoter was HIF1-α dependent, and melatonin degraded HIF1-α in melanoma cells." (PMID 31023624, 2019). "Additionally, we demonstrated that the melatonin exerted its antitumor effect via HIF1-α mediated Ku80/PDK1 pathway in part, and downregulation of Ku80 enhanced the antitumor effect of melatonin in melanoma." (PMID 31023624, 2019). "Based on our observations in present study, luteolin may play a direct role in the degradation of HIF‐1α and subsequent VEGF signaling in melanoma cells, leading to the inhibition of hypoxia‐induced tumor angiogenesis." (PMID 30653763, 2019). "Collectively, our study demonstrated that Ku80 promoted melanoma growth and regulated antitumor activity of melatonin by targeting HIF1-α dependent PDK-1 signaling pathway, suggesting that Ku80 may be a potential molecular target for melanoma treatment." (PMID 31023624, 2019). "In addition, we performed silencing HIF-1α and HIF-2α in the BrafV600E; Phd2−/− melanoma cells and showed a decreased activation of Akt pathway." (PMID 30575721, 2018).
melanoma (continued). "HIF inhibitor or HIF-1α knockdown suppresses AKT–mTOR pathway in BrafV600E; Phd2−/− melanoma cells, supporting the involvement of HIF pathway activation in mediating the effect of Phd2 deletion, at least in melanoma setting." (PMID 30575721, 2018). "The results of our study showed that CIRBP could induce HIF-1α protein production via a CIRBP-mediated increase in mRNA stability in BCa, and the same results had been reported in Melanoma LOX-IMVI cells in a study by Chang et al51." (PMID 30315244, 2018). "Our results indicate that HIF1α and SOX2 are inversely correlated in normoxic condition, and this effect might be functionally sufficient to reprogram melanoma cells toward OxPhos." (PMID 30466459, 2018). "Moreover, HIF-1α knockdown retarded the α-MSH-induced autophagosome formation and apoptosis in melanoma cells, implicating the pivotal role of HIF-1α activation in α-MSH-induced cell death." (PMID 30062060, 2018). "Because of the Bcl-2 family such as BNIP3 and BNIP3L were triggered by HIF-1α in autophagic process, we next evaluated whether α-MSH modulated the Bcl-2 family gene expression in melanoma cells during hypoxia." (PMID 30062060, 2018). "Finally, it was delineated that α-MSH stimulated the HIF-1α signaling as well as the expression of BNIP3/BNIP3L, thereby promoting the autophagy and apoptosis in melanoma cells." (PMID 30062060, 2018). "Similar results were observed after BrafV600E; Phd2−/− melanoma cells cultured under 1% oxygen or expression of a non-degradable HIF-1α." (PMID 30575721, 2018). "Moreover, our results further demonstrated that silencing HIF-1α by RNA interference abolished the α-MSH-stimulated autophagy genes' expression and eventually retarded α-MSH-induced apoptosis in melanoma cells during hypoxia." (PMID 30062060, 2018). "Phd2 deletion results in stabilization of HIF-1α and HIF-2α in BrafV600E; Phd2−/− melanoma cells." (PMID 30575721, 2018). "HIF-1α and c-myc are important transcription factors for the extrahepatic regulation of ASS, and the interplay between HIF-1α, c-myc, and Sp4 determines the expression of ASS in melanoma cells in the context of varying degrees of arginine availability." (PMID 28791021, 2017). "Using IHC and HIF-1α on FFPE serial sections, we could identify non hypoxic (A1) and hypoxic zones (A2, A3, A4, A5) in primary melanoma from 4 patient tissues." (PMID 29312568, 2017). "Furthermore we enriched for HIF1A protein prior to testing for MHA-3 reactivity, since HIFs have been shown to be instrumental for driving melanoma metastasis." (PMID 27853253, 2016). "These seem to play an important role in melanoma, where HIF1α is constitutively expressed – a fact, which is not necessarily due to the prevalence of hypoxic conditions." (PMID 26000250, 2015). "Although HIF1α is already expressed in nevi, most likely as a result from the mild hypoxic conditions, which occur in skin, HIF1 expression and activity is increased in melanoma and correlates with decreased differentiation and VEGF expression." (PMID 26000250, 2015). "HIF-1α was found under normoxic conditions in malignant melanoma cells, but not in normal human melanocytes." (PMID 26547841, 2015). "In melanoma, oncogenic BRAFV600E promotes the mRNA and protein expression of GLUT-1, GLUT-3, and HK2 through the involvement of several transcription factors including HIF-1α, c-Myc, and MONDOA." (PMID 26713093, 2015). "Using a metastatic human melanoma cell line (WM9), we compared the time and concentration dependent ability of AA or ascorbate-2-phosphate (A2P), an oxidation-resistant analog of AA, to decrease the level of HIF-1α protein." (PMID 26547841, 2015). "In a genetic mouse melanoma model driven by melanocyte-specific BrafV600E induction and Pten depletion, HIF1α is required for angiogenesis and metastasis without affecting primary tumor formation." (PMID 26000250, 2015).
melanoma (continued). "The protein expression of other transcription factors, namely STAT3, a known critical regulator of melanoma development, and HIF-1α and HIF-2α, respectively, were not influenced by diclofenac." (PMID 23874405, 2013). "It has also been shown that the treatment of human A2058 melanoma cells with a small-molecule STAT3 inhibitor, CPA-7 was effective at inhibiting the expression of HIF-1α and VEGF in vitro and tumour growth and angiogenesis of human A2058 melanoma tumours in vivo." (PMID 23301832, 2013). "As with miR-33a, the prognostic or functional relevance of miR-424 has not been studied in melanoma, but roles have been previously defined for miR-424 in HIF-1α/HIF-2α mediated angiogenesis and regulation of monocyte/macrophage differentiation." (PMID 22857597, 2012). "In agreement with our results in melanocytes, HIF1α silencing in SBcl2 melanoma cells did not interfere with downregulation of secreted PEDF protein levels by hypoxia." (PMID 22457728, 2012). "To investigate the subcellular origin of HIF-1α and TACO-1, we performed immunoblot analysis comparing whole-cell lysates with mitochondrial extracts prepared from Elesclomol-treated melanoma cells, which showed that TACO-1 was decreased in mitochondrial extracts." (PMID 22912665, 2012). "Hypoxia-inducible factor 1 α (HIF1α) has also been demonstrated to be activated at the transcription level by direct MITF binding to the HIF1α promoter region and acts as an antiapoptotic factor in melanoma cells." (PMID 22046555, 2011). "The observation that Arg deprivation induces up-regulation of c-Myc but down-regulation of HIF-1α in some melanoma cells but not in others is intriguing." (PMID 21152246, 2010). "These knock down studies suggest that increased non-hypoxic expression of HIF-1α plays an important role in key malignant properties exhibited by these human melanoma cells." (PMID 19919690, 2009). "We have examined the normoxic expression of HIF-1α RNA and protein in normal human melanocytes and a series of human melanoma cell lines isolated from radial growth phase (RGP), vertical growth phase (VGP) and metastatic (MET) melanomas." (PMID 19919690, 2009). "Studies in non-small cell lung cancer and malignant melanomas showed that HIF-2α expression was related to a poor outcome when HIF-1α was not." (PMID 17179985, 2007). "As PKM2 and HIF-1α both play important roles in the metabolic reprogramming process, it is reasonable to believe that the interactions between TIPE and these two molecules could affect the glycolysis in melanoma." (PMID 39728923, 2024). "However, there is a lack of relevant research investigating how celastrol regulates the expression of HIF-1α and the PI3K/AKT/mTOR signaling pathway to treat B16-F10 melanoma cells, and the precise mechanism involved remains unclear." (PMID 38771435, 2024). "This review discusses the inhibition of angiogenesis through the upregulation of PTEN and the inhibition of hypoxia-inducible factor 1 alpha (HIF-1-α) in human malignant melanoma, as no targeted therapies have been approved by the FDA for the inhibition of angiogenesis in human malignant melanoma." (PMID 38338464, 2024). "Here, we demonstrate that a selective-HDAC8 inhibitor functions as an indirect inhibitor of HIF-1α and may be an effective therapeutic strategy in treating not only melanoma but also other solid tumors." (PMID 36831463, 2023). "Nevertheless, HIF-1α is subject to regulation independent of oxygen levels, underscoring the complex interplay between oxygen-dependent and oxygen-independent mechanisms in determining the pathogenesis of melanoma." (PMID 38057843, 2023). "The limitations of the current study are as follows: we could not evaluate HIF-1α expression in melanoma tissues treated with radiation therapy." (PMID 36669005, 2022).